CFTR (CF transmembrane conductance regulator)
Diseases named in the same sentence as CFTR in open-access papers (continued):
Sharing a sentence is not in itself a finding about the gene and the disease.
breast carcinoma (continued). "The addition of TGF-β1 to non-invasive breast cancer cells caused the cells to undergo type-3 EMT as seen by the decrease in E-cadherin, but interestingly CFTR was also down-regulated." (PMID 30021582, 2018). "Ectopic overexpression of CFTR in breast cancer cell lines downregulates EMT markers and suppresses cell invasion and migration in vitro, as well as metastasis in vivo." (PMID 29463274, 2018). "CFTR downregulation correlates with poorer clinical prognosis of patients with mammary carcinoma." (PMID 36941680, 2023). "CFTR knockout mice model showed reduced breast cancer implantability and decreased growth rate." (PMID 36941680, 2023). "The risk of breast cancer before the age of 40 didn ́t differ in F508del CFTR mutation carriers and non-carriers." (PMID 36941680, 2023). "As CFTR modulators affect the mammary gland and the effect of the rest of the drugs is unclear, further research is needed to understand the links between the therapy and the increasing incidence of breast cancer." (PMID 36941680, 2023). "In addition, low levels of the CFTR protein correlate with a poor survival of patients with breast cancer." (PMID 37175647, 2023). "Accordingly, our cell culture experiments showed that citrate activated hyaluronan export from breast carcinoma cells, stimulated iodide efflux from epithelial cells carrying normal CFTR as well as ΔF508-CFTR and recovered it from premature intracellular degradation." (PMID 36296967, 2022). "Moreover, CFTR suppresses the progression of many other cancer types, such as lung cancer, breast cancer, nasopharyngeal carcinoma, and prostate cancer." (PMID 34830864, 2021). "Single CFTR mutation carriers are more susceptible to cystic fibrosis-related conditions, and monoallelic ATM mutation carriers have higher risks for cancers and ischemic heart disease—especially breast cancer in female carriers." (PMID 33448283, 2021). "More recently, promoter hypermethylation of CFTR was found in breast cancer." (PMID 32365523, 2020). "Interestingly, while in prostate cancer CFTR was reported to upregulate tumour suppressor miR-193b (which suppresses uPA), in breast cancer CFTR seems to repress uPA by inhibiting NF-κB, a known uPA activator." (PMID 32365523, 2020). "Another study reported that a lack of CFTR promoted proliferation associated with an increase of extracellular ATP in breast cancers." (PMID 32182826, 2020). "Currently, there is evidence that a violation of the expression of the CFTR gene is related to the development of cancer not only of the gastrointestinal tract, but also of other types of cancer: head and neck, non-small cell lung cancer, bladder, liver (hepatocellular cancer) and breast cancers." (PMID 37175647, 2023). "Survival analysis of ion channels interacting with EMT-related genes showed KCNN4 (p-value: 0.071), CFTR (p-value: 0.16), KCNJ10 (p-value: 0.17), VDAC1 (p-value: 0.000003) and VDAC2 (p-value: 0.052) the level of expression associated with survival of breast cancer patients." (PMID 35326596, 2022). "Down regulation of CFTR expression and/or mutations that disrupt CFTR function have been reported in non-small-cell lung cancer (NSCLC), glioblastoma, bladder cancer, esophageal cancer, pancreatic cancer, nasopharyngeal cancer, prostate cancer, and breast cancer." (PMID 32326161, 2020). "Of note, a previous study reported that downregulation of CFTR was associated with a proportional downregulation of E-cadherin and activation of NFκB/uPA, resulting in disruption of cell polarity, induction of epithelial-to-mesenchymal transition (EMT), and invasion in breast cancer." (PMID 32182826, 2020). "Deep deletions were significantly more prevalent in prostate cancer than in breast cancer, with frequent occurrences in ABCG2, ABCG1, ABCC4, ABCA2, ABCC2, ABCC7/CFTR, and ABCC9." (PMID 40641097, 2025).
breast carcinoma (continued). "Specific ion channels in various aspects of EMT induction have been reported, including the downregulation of CFTR, an ion channel that promoted EMT, migration and invasion in breast cancer." (PMID 35326596, 2022). "This is the case for breast cancer, where the EMT-suppressing effect of CFTR (i.e., increase in the levels of E-cadherin and decrease in the levels of vimentin) was associated with its ability to inhibit both NF-κB and uPA." (PMID 32365523, 2020). "Accordingly, patients with low CFTR, CLCA2 or CLCA4 mRNA abundance in breast cancer specimens have higher odds of developing metastases and a decreased relapse-free survival (green)." (PMID 27618016, 2016). "Interestingly, apart from LC (2 events), fusions with CFTR were detected in 1 GEC and 1 breast cancer case in the forms of MET‐CFTR and CFTR‐MET, respectively." (PMID 37326363, 2023). "As CHIP-dependent degradation of newly synthesized CFTR occurs in the ER, through ERAD, we asked whether a similar process accounts for CHIP-dependent degradation of newly synthesized ErbB2 in ErbB2-overexpressing breast cancer cells." (PMID 34439093, 2021). "While EMT is less understood in the pathology of CF, studies do show the involvement of CFTR in the EMT process, particularly in Type 3 EMT, where there has been compelling evidence of its involvement in cancer progression in lung, gut, liver and breast cancer." (PMID 30021582, 2018).
lung carcinoma (33 papers, 2010 to 2025). "Conversely, in a case control study of 574 lung cancer patients and 679 control patients, CFTR F508del was associated with a 68% reduced risk for lung cancer." (PMID 41147257, 2025). "DNA methylation is also associated with lung cancer prognosis and is essential for its growth and metastasis.In this article, we discuss the role of CFTR and PKIA methylation in lung cancer, as revealed by data analysis from TCGA and GEO." (PMID 37644544, 2023). "Nicotine is a potential cause of lung cancer and a progressive enhancer of adenocarcinoma cells that inhibits the CFTR protein expression in A549 cells." (PMID 35205604, 2022). "Studies reported that CFTR acts as a tumor suppressor and is downregulated in lung cancer, and dysfunctional CFTR is associated with cancer progression." (PMID 36110953, 2022). "The clinical association of CFTR expression with lung cancer patient prognosis was further investigated in vitro." (PMID 35715537, 2022). "Moreover, the genetic mutations in the CFTR gene, resulting in CFTR dysfunction, may also contribute to an altered cellular environment that favors the development of lung cancer." (PMID 37686519, 2023). "CFTR gene methylation occurs in various tumors, including lung cancer, serving as a mechanism by which tumor cells suppress tumor suppressor genes." (PMID 40433361, 2025). "For example, studies have shown that CFTR is overexpressed in several types of cancer, including breast, colon, and lung cancer." (PMID 37984883, 2024). "Hazard ratio(HR) > 1 represents high-risk genes, HR < 1 represents low-risk genes, and found that CFTR and PKIA genes (P < 0.05) have prognostic significance in lung cancer." (PMID 37644544, 2023). "The role of the CFTR in CF and its relationship to lung cancer have been the focus of scientific investigation." (PMID 37686519, 2023). "In the context of previous results, these data indicate that CFTR is directly involved in lung cancer onset and progression and that CFTR thus constitutes a promising target for adjuvant therapy by repurposing already approved CFTR agonists." (PMID 35715537, 2022). "A link between CS, downregulation of CFTR, and lung cancer was reported in a study that correlated CS and CFTR downregulation with enhanced oncogenesis in A549 lung cancer cells." (PMID 32326161, 2020). "The expression of the cystic fibrosis transmembrane conductance regulator (CFTR) gene has been reported to be related to multidrug-resistance in lung cancer patients." (PMID 31839819, 2019). "The incidence of lung cancer is gradually increased, and the cystic fibrosis transmembrane conductance regulator (CFTR) has recently demonstrated to have an implication in the deoncogenesis and malignant transformation of many types of cancers." (PMID 29526175, 2018). "Consistent with the finding in NPC in the present study, we have previously reported that low CFTR expression is correlated with cancer progression and poor prognosis in prostate, breast, colon and lung cancers." (PMID 27769067, 2016). "Our equivalent data from a lung cancer cell line suggest that functional wild type CFTR can act as a brake on inflammation." (PMID 20644644, 2010). "Issues such as drug resistance in TB, incorrect inhaler use in COPD, certain CFTR mutations that do not respond to CFTR modulators in CF, and immune-related side effects in lung cancer therapies further complicate their management." (PMID 40124344, 2025). "Due to the small sample size it is unclear whether this could signal a potential protective role of CFTR PV against lung cancer, but should be further evaluated in future studies." (PMID 41147257, 2025). "Indeed, CFTR expression was negatively correlated with the prognosis of patients with lung cancer, and metaanalysis confirmed that adults with CF had 5–10 times higher risk to develop colorectal cancer than the general population." (PMID 36602863, 2023). "We identified two lung cancer-specific methylation markers, CFTR and PKIA." (PMID 37644544, 2023).
lung carcinoma (continued). "DNA methylation might be crucial for the downregulation of CFTR gene expression in lung cancer, and promoter hypermethylation of CFTR could also be an important prognostic factor in NSCLC." (PMID 35311093, 2022). "Similarly, in vitro exposure of lung cancer cells to nicotine resulted in reduced CFTR expression and increased cell migration, thus providing a potential link between smoking and disease aggressiveness." (PMID 35715537, 2022). "Although not much is known about its function aside from its involvement in lung cancer, it will be interesting to further explore this interaction given the putative role that wt‐CFTR plays in protection from epithelial‐mesenchymal transition (EMT) and cancer." (PMID 35156780, 2022). "Looking at the CFTR levels in lung cancer patients, it could be of great interest to further decipher the contribution of the mucins in response to anti-PD-1 or anti-PD-L1 monoclonal antibodies." (PMID 32516941, 2020). "It is tempting to speculate that treatment with CFTR modulators could be of benefit in lung cancer patients with COPD." (PMID 32516941, 2020). "The CFTR exhibited an inhibitory role in the malignancy of lung adenocarcinoma A549 cells, suggesting that it may be a novel potential target for lung cancer treatment." (PMID 29526175, 2018). "Moreover, a significant correlation has been reported between CFTR downregulation and lung cancer progression and metastasis." (PMID 29062084, 2017). "On the other hand, AAbs can lead to the development of lung cancer by blocking CFTR." (PMID 29062084, 2017). "Furthermore, down-regulation of CFTR has been correlated with cancer progression, and proposed to be a prognostic predictor for lung cancer, breast cancer and colon cancer." (PMID 27769067, 2016). "In lung cancer, only the clustered cell-like subpopulation significantly expresses FOXI1, which serves as a major regulator of ionocytes and a primary source of CFTR activity." (PMID 40568194, 2025). "Our study shows that the methylation status of CFTR and PKIA can be used as potential prognostic biomarkers and therapeutic targets in lung cancer, and their prognostic value needs to be further explored to improve the survival prediction of patients." (PMID 37644544, 2023). "Our study revealed that the methylation status of CFTR and PKIA can serve as potential prognostic biomarkers and therapeutic targets in lung cancer." (PMID 37644544, 2023). "Enhanced CFTR expression inhibits various cancerous processes such as EMT in breast carcinoma, lung cancer, NPC, endometrial carcinoma cells, prostate cancer, and intestinal carcinoma." (PMID 35205604, 2022). "In human lung cancer cells, KCNQ1 acts to regulate basal cAMP-stimulated Cl− secretion through the cystic fibrosis transmembrane conductance regulator (CFTR)." (PMID 35216393, 2022). "This first reported case of ALK-positive lung cancer in a CF patient highlights the need to consider malignancy in atypical exacerbations and to be mindful of potential interactions between ALK inhibitors and CFTR function." (PMID 40563468, 2025). "Intriguingly, cystic fibrosis transmembrane conductance regulator (CFTR) protein, an epithelial anion channel that transports Cl- across epithelial surfaces, such as the respiratory tract, is diminished in lung cancer." (PMID 37381723, 2023). "In contrast, this site is not accessible in ATAC‐seq nor is it enriched for RNAPII in Calu3, a lung carcinoma cell line that also expresses CFTR, nor primary bronchial epithelial cells." (PMID 37269165, 2023). "We found that the methylation of CFTR and PKIA genes correlated with the prognosis of lung cancer." (PMID 37644544, 2023). "While these combined genetic and epigenetic findings strongly indicate that CFTR expression levels constitute a strong biomarker for lung cancer outcomes, they do not provide information about whether suppression of CFTR is a consequence of cellular transformation or might act as an upstream driver." (PMID 35715537, 2022).
Meconium ileus (32 papers, 2007 to 2026). Obstruction of the intestine due to abnormally thick meconium. "The risk for a patient to present with meconium ileus (MI) is 24.9% if he has two copies of F508del mutation, 16.9% if he has one F508del paired with another mutation and 12.5% for two other CFTR mutations." (PMID 38893705, 2024). "Meconium ileus at birth is associated with worse lung function later in life, suggesting more severe CFTR dysfunction and greater respiratory compromise." (PMID 39564025, 2024). "Inactivating mutations in CFTR lead to meconium ileus in the newborn and intestinal obstructions in adults due to a reduction in gut motility and hydration." (PMID 34546338, 2021). "Meconium ileus occurs almost exclusively in individuals with severe CFTR mutations known to confer pancreatic exocrine insufficiency (~90% of the CF population), therefore modifier gene studies of meconium ileus have been restricted to this CF sub-population." (PMID 30807572, 2019). "Meconium ileus is the earliest manifestation of CF occurring in up to 20% of the patients and is associated with certain CFTR mutations including p.Phe508del." (PMID 24649380, 2014). "Loss of prosecretory CFTR activity is thought to be the principal cause of gastrointestinal disorders in CF, including chronic constipation, which has up to 47% prevalence, as well as the less common but more serious meconium ileus and DIOS." (PMID 34100381, 2021). "The meconium ileus association is seen in patient cohorts composed of many different CFTR genotypes, and the effect size is similar in individuals who are Phe508del/Phe508del (OR = 1.41, se = 0.058) versus other CFTR genotypes (OR = 1.32, se = 0.083)." (PMID 30807572, 2019). "Mutations in the CFTR gene are responsible for both the classical and atypical presentations of the disease, including pulmonary disease, pancreatic insufficiency, malabsorption, meconium ileus, failure to thrive, infertility, and elevated concentrations of chloride in sweat." (PMID 24649380, 2014). "Our aim was to assess the effect of the CF-GI clinic and CFTR modulators on GI complications with incidence of distal intestinal obstructive syndrome (DIOS)." (PMID 40720490, 2025). "The lung manifestation of CF was high in CFTR−/− pigs, but the early death of the animals due to meconium ileus limits their use as a CF model." (PMID 38474149, 2024). "Although this did not result in statistically significant GxG interaction (interaction p = 0.057), the dependence on CFTR genotype of the ATP12A-meconium ileus relationship requires further investigation." (PMID 30807572, 2019). "The pig and murine models have highlighted the engagement of the gastrointestinal tract, where confined restoration of CFTR is sufficient to ameliorate both meconium ileus and the intestinal obstruction phenotypes to substantial degrees." (PMID 30807572, 2019). "CFTR-knockout ferrets recapitulated many disease similarities to humans including defective airway Cl− transport, meconium ileus, and the spontaneous development of bacterial lung infections." (PMID 30405068, 2018). "Creating a “gut corrected” CF pig expressing CFTR in the gastrointestinal tract by the fatty acid binding protein (FABP) promoter alleviated meconium ileus, making longitudinal studies more feasible." (PMID 30405068, 2018). "Twelve of the 16 very young children with CF had severe genotypes, and the other four had meconium ileus, likely reflective of severe CFTR genotype." (PMID 29222447, 2017). "Male and female CFTR+/- pigs were crossed and the progeny was examined by computed tomography (CT) scan to detect the presence of meconium ileus and facilitate a rapid post-natal surgical intervention." (PMID 26600426, 2015). "CT scan imaging of meconium ileus is an accurate method for rapid identification of CFTR-/- piglets." (PMID 26600426, 2015). "The CFTR−/− rat model shares the problem of early postnatal death due to meconium ileus." (PMID 38474149, 2024).
Meconium ileus (continued). "However, CFTR-/- pigs presents a 100% prevalence of meconium ileus that leads to death in the first hours after birth, requiring a rapid diagnosis and surgical intervention to relieve intestinal obstruction." (PMID 26600426, 2015). "Early CT detection of meconium ileus may help to extend the lifespan of CFTR-/- piglets and, thus, improve experimental research on CF, still an incurable disease." (PMID 26600426, 2015). "Modifiable risk factors like maternal education, home stability, and early CF therapy significantly improve lung health outcomes in CF, while non-modifiable factors like CFTR genotype and meconium ileus predict poorer outcomes." (PMID 39564025, 2024). "Though mice lacking CFTR have been used as a model for the CF gastrointestinal tract and pancreas, they lack MI development but instead develop a distal intestinal obstruction syndrome-like phenotype postnatally without dietary modifications." (PMID 38665380, 2024). "Moreover, unlike the CF ferret or pig, the CFTR−/− rat does not present with meconium ileus at birth." (PMID 24608905, 2014). "With the eQTL findings pointing to the pancreas, the common allele variants in ATP12A that associated with meconium ileus risk are also associated with increased ATP12A expression, where even modest increases in proton secretion, may be critical in the absence of CFTR." (PMID 30807572, 2019). "Moreover, 3 out of 9 CFTR-/- piglets that were not subjected to CT scan diagnosis and early surgery had already started to develop early signs of intestinal perforation and peritonitis, probably due to excessive pressure in the intestines by the meconium ileus and food ingestion." (PMID 26600426, 2015).